SFRP2 (secreted frizzled related protein 2)
Diseases named in the same sentence as SFRP2 in open-access papers (continued):
Sharing a sentence is not in itself a finding about the gene and the disease.
tumor (continued). "The top 5 overexpressed proteins in tumor compared to NT (ranked according to the log2(FC) T vs CT) included SFRP2, KDM5A, CMTM5, HSPA5 and FN1." (PMID 39681068, 2024). "SFRP2 can act as a Wnt-suppressing or -activating factor in different tissue contexts and, therefore, exert tumour-suppressive or -promoting roles." (PMID 38361045, 2024). "The results showed that LPL is still under-expressed in tumor cells and that SFRP2 is overexpressed in all HER2, Luminal A, and Luminal B subtype groups, and under-expressed in the Basal_like subtype group." (PMID 38791477, 2024). "The results showed that the combined detection of RNF180 and SFRP2 genes outperformed traditional tumor markers in GC diagnosis, with a sensitivity of 85.4 % and specificity of 76.9 %." (PMID 39541711, 2024). "As secreted glycoproteins, SFRP1 and SFRP2 are thought to be primarily tumor suppressive as they bind and sequester WNT ligands to modulate cancer cell growth, cell polarity, transformation and cancer stem cell activity." (PMID 37091166, 2023). "It is important to note that expression of SFRP2 and the presence of SFRP2+ fibroblast in OC tumor tissues are still in need of further experimental validation." (PMID 38069266, 2023). "To date, dysregulated SFRP2 has been reported to involve in a series of physiological or pathological processes, for instance, cellular differentiation, tumor metastasis, drug resistance and functional alterations of stem cells 33-35." (PMID 36860682, 2023). "The following year, the team found that sFRP2 inhibits tumor growth and invasion by regulating the wnt signaling pathway." (PMID 37780610, 2023). "Seven hub genes, REG4, S100A7, CLCA1, FABP4, RETNLB, SFRP2, and WNT10A, were all significantly associated with CC patient prognosis and differentially expressed in normal and tumor tissues." (PMID 36941538, 2023). "Significantly higher SFRP2 protein levels were found in the tumour samples collected from patients with pleural invasion PL2 in comparison to the patients with PL1 NSCLC (214.96 vs. 103.05; p = 0.016)." (PMID 37999144, 2023). "For the SCC subtype, a lower SFRP2 concentration in tumour specimens than in NT was observed (p = 0.028)." (PMID 37999144, 2023). "In contrast, inflammatory CAFs were dominant within tumor-distal subsets and expressed complement components and the Wnt-inhibitor SFRP2." (PMID 37350578, 2023). "Zebularine can be incorporated into DNA and form covalent complexes with DNMT to competitively inhibit DNMT activity, demethylate tumor suppressor genes, such as SFRP2, Dkk3, and p16, and inhibit tumor cell proliferation, differentiation, and metastasis." (PMID 37056286, 2023). "Sfrp2 has been shown to be decreased in several tumor types as a tumor suppressor, but has also been shown to activate tumor angiogenesis, as a tumor promoter." (PMID 37103052, 2023). "Many of the DEGs were involved in ferroptosis (Ptgs2), enhanced T-cell function (Lef1), regulators of EMT (Zeb1, Zeb2, Vimentin, and Sfrp2), and fibrosis (Col1α1 and Acta2) in the tumor microenvironment." (PMID 36835036, 2023). "Analysis of the total NSCLC group showed significantly lower SFRP2 protein concentration in tumour samples than in the NT tissue (189.45 vs. 614.22) (p < 0.001)." (PMID 37999144, 2023). "Increased concentrations of SFRP1 and SFRP5 were present in stage III NSCLC samples, while the tumour samples with high pleural invasion (PL2) had an increased level of SFRP2." (PMID 37999144, 2023). "For the AC subtype, significantly higher concentrations of SFRP1 and SFRP5 in tumour samples compared to NT were detected (p = 0.022 and p = 0.011, respectively), while the level of SFRP2 protein was reduced in tumour samples (p < 0.001)." (PMID 37999144, 2023). "We identified DEGs such as VCAN, SFRP2 involved in angiogenesis and epithelial-mesenchymal transition, which can be developed as novel tumor-agnostic biomarkers for tumor progression." (PMID 37965470, 2023).
tumor (continued). "A range of genes showed increased expression within stromal populations distal from tumor including the C3 component of complement and SFRP2, a soluble modulator of Wnt signaling." (PMID 37350578, 2023). "In the multivariate analysis, stroma with high SFRP2 expression and high tumor stage were significantly prognostic for inferior DSS and MeFS (all p < 0.001)." (PMID 35372028, 2022). "Accordingly, we also found that high stromal SFRP2 expression, low tumoral SFRP2 expression, and high tumor stage and histological grade were significantly correlated with poor local recurrence-free survival (LRFS) (all p < 0.0414) in the univariate analysis." (PMID 35372028, 2022). "Upregulated genes included cartilage-associated genes (COMP, MATN3, and COL11A2), collagen- and extracellular matrix-associated genes (COL9A2, SFRP2, and SERPINE2), and tumor metastasis- and progression-associated genes (SLC38A3, FST, ITGA11, and DGKI)." (PMID 36192442, 2022). "Although SFRP2 was shown to act as tumor suppressor in CRC cell lines and SFRP2 methylation is a hallmark of CRC tumor cells, the clinical prognosis of SFRP2 methylation is contradictory." (PMID 35892888, 2022). "DPT and SFRP2 were rarely expressed in normal epithelial cells and tumor immuno-microenvironment cells but were mainly expressed in fibroblasts from tumor tissues." (PMID 36104333, 2022). "SFRP1 and SFRP2 are expressed in stromal myofibroblasts and are downregulated from typical adjacent tumor (normal tissue adjacent to the tumor, NAT) tissues toward the tumor." (PMID 35712512, 2022). "Since KIF5B and SFRP2 had consistent staining in benign and tumor tissue as well as in metastases, they can be considered strong markers and incredibly valuable diagnostically." (PMID 36002889, 2022). "In the UBUC group, we detected remarkable correlations between low tumoral SFRP2 expression and high tumor stage (p = 0.004), the presence of vascular invasion (p = 0.039), and high mitotic activity (p = 0.002)." (PMID 35372028, 2022). "LINC00261 was significantly upregulated by fucoidan in HCC cells and then acted as a tumor suppressor gene by regulating the miR-522-3p/secreted frizzled-related protein 2 (SFRP2) signaling pathway to inhibit cell proliferation and invasion." (PMID 36532760, 2022). "Secreted frizzled-related protein 2 (SFRP2) was significantly decreased and later confirmed in functional studies, suggesting SFRP2 had tumor suppressor properties downregulating Wnt pathway." (PMID 33808624, 2021). "In vitro phenotype analyses after SFRP2-overexpression in U-2987 revealed significantly decreased tumor sphere formation, self-renewal capacity, as well as cell proliferation, and increased Matrigel invasive capacity." (PMID 34021259, 2021). "The upregulation of SFRP2 in the tumor vasculature suggests a link between SFRP2 and tumor angiogenesis." (PMID 33140138, 2021). "A major recent finding is the upregulation of SFRP2 in the tumor vasculature, suggesting it being a specific marker of tumor endothelial cells." (PMID 33140138, 2021). "Analysis of human tumor tissue spatial gene expression patterns showed distinct expression of SFRP2- and SOX2-correlated genes in vascular and cellular areas, respectively." (PMID 34021259, 2021). "To enhance insight in oncogenic role of SFRP2, we performed a literature study about SFRP2 in Wnt signaling and tumor angiogenesis." (PMID 33140138, 2021). "Direct proof for the tumor promoting effect of SFRP2 can be obtained from in vivo tumor mouse models." (PMID 33140138, 2021). "In endothelial and tumor cells, SFRP2 binds to the FZD5 receptor and stimulates the calcineurin/NFATc3 pathway." (PMID 34070758, 2021). "Secreted frizzled-related protein 2 is a secreted protein involved in WNT signaling in tumor and endothelial cells." (PMID 34070758, 2021).
tumor (continued). "Since tumor angiogenesis is an important process in tumorigenesis and metastasis formation, specific tumor endothelial markers such as SFRP2 show great promise as targets for anti-cancer therapies." (PMID 33140138, 2021). "Phenotypically, SFRP2 decreased tumor sphere formation, stemness as assessed by limiting dilution assay, and overall cell proliferation but increased cell motility, whereas SOX2 induced the opposite effects." (PMID 34021259, 2021). "SFRP2 has previously been reported as an anti-oncogene whose methylation has been shown to accelerate cancer cell invasion and growth during tumor progression." (PMID 34205081, 2021). "As an example in vivo, SFRP2-targeted molecular imaging shows that SFRP2 is highly expressed in tumor vessels with low uptake in adjacent normal vessels or renal vessels." (PMID 34070758, 2021). "On the contrary, (over)expression of SFRP2 in cancer cell lines and tumor tissues has also been described." (PMID 33140138, 2021). "Although VEGF was decreased during aging, thereby reducing response to bevacizumab, angiogenesis was increased because of an increase of Secreted Frizzled Related Protein 2 (sFRP2), a modulator of Wnt signalling, in the aged tumor microenvironment." (PMID 33964953, 2021). "The studies of Fontenot and Garcia provide valuable information on the potential use of anti-SFRP2 antibodies to reduce tumor growth and tumor angiogenesis." (PMID 33140138, 2021). "The fact that SFRP2 is found to be downregulated in a large number of tumor types suggests a tumor suppressor role of the glycoprotein." (PMID 33140138, 2021). "To better understand the differences between tumours with POLE mutations and the other subtypes, we evaluated the methylation status of discrete regions within the promoter of the MGMT and SFRP2 genes." (PMID 34034807, 2021). "The expression among tumor stages varied significantly for SFRP2, SFRP3, and SFRP4, whereas the mRNA expressions of SFRP1 and SFRP5 were not markedly different." (PMID 34205081, 2021). "The relationship between SFRP2 expression and tumor growth was further explored in murine tumor models." (PMID 33140138, 2021). "Several studies investigated the functional role of SFRP2 in the tumor vasculature, showing that SFRP2 binds to FzD receptors on the surface of tumor endothelial cells." (PMID 33140138, 2021). "Our data indicated that low SFRP2 expression was positively correlated with larger tumor size, advanced tumor stage, radiotherapy treatment and radioresistance." (PMID 34852024, 2021). "The available evidences suggest that SFRP2 can be oncogenic or tumor suppressive in cancers, which is quite contradictory." (PMID 34852024, 2021). "In the present study, plasma SFRP2 was elevated in mice with OS lung metastases compared to tumor-free mice in two cell lines, and plasma SFRP2 was reduced in all treatment groups." (PMID 34070758, 2021). "This provides evidence that SFRP2 antagonism not only results in the inhibition of angiogenesis and the induction of tumor apoptosis, as previously reported, but also demonstrates immunotherapeutic activity." (PMID 34070758, 2021). "Proteins such as SFRP2, that seem to be specifically (over)expressed in the tumor vasculature, show great promise as therapeutic targets in the fight against cancer." (PMID 33140138, 2021). "The glycoprotein SFRP2 is shown to be a key player in the process of tumor angiogensis, an important process in tumor formation and progression." (PMID 33140138, 2021). "The serum concentration of SFRP2 was increased in control tumor-bearing mice (8.91 ± 0.67 ng/mL), compared to non-tumor-bearing mice (3.36 ± 0.74 ng/mL, n = 3; p < 0.01)." (PMID 34070758, 2021). "Secreted frizzled-related protein 2 (SFRP2) promotes metastatic OS cell migration and tumor angiogenesis." (PMID 34070758, 2021). "We found that SFRP2 promoter methylation was positively correlated in tumor area with insulin and HOMA-IR but negatively correlated with HDL-c." (PMID 32517740, 2020).
tumor (continued). "The promoter methylation of SFRP2 was also positively correlated in adjacent tumor-free area with insulin." (PMID 32517740, 2020). "As far as we understand, SFRP2 functions as a tumor suppressor gene by binding to Wnt protein as antagonist and inhibiting Wnt signaling pathway." (PMID 32517740, 2020). "Both TIAM1 and SFRP2 hypermethylation leads to decrease expression of both genes and further increase cell proliferation and tumor growth." (PMID 32517740, 2020). "When we compared CRC tumor tissue, SFRP2 promoter methylation was significantly decreased in the > 30th CRC group than in the < 30th CRC group (p < 0.01)." (PMID 32517740, 2020). "Serum sFRP2 levels were correlated with the tumor size, TNM stage, and lymph node metastases status (P < 0.05)." (PMID 30944668, 2019). "Monoclonal antibody-mediated inhibition of Sfrp2 has been show to reduce tumor growth and prolong survival in a mouse model of TNBC." (PMID 31299925, 2019). "In univariate Cox regression analysis, menopausal status, ER status, tumor size, lymph node status, TNM stage, and serum sFRP2 concentration were significantly correlated with the risk of poor prognosis (P < 0.05)." (PMID 30944668, 2019). "Recently, we have reported that the hyper-methylation of the SFRP2 promoter exhibited a strong correlation with BMI in tumor samples, consequently suggesting adiposity as a prognostic factor in patients with CRC." (PMID 31319558, 2019). "In the stage 2 analysis, five markers accurately discriminated between neoplasia and control samples with p < 0.0001 – SFRP2, SFRP4, WIF1, APC1A and APC2; with between 40% and 76% increases in geometric mean values." (PMID 30473377, 2019). "The results revealed hyper-methylation of the SFRP2 promoter, since SFRP2 methylation in tumor tissue was significantly higher (40.30%)in comparison to the levels obtained for adjacent tumor-free tissue areas (17.86%)." (PMID 31319558, 2019). "We suggest that future studies investigating the role of SFRP2 or 4 in tumourigenesis consider possible contribution by the tumour microenvironment and incorporate this into model choice." (PMID 28218291, 2017). "For example, cell proliferation is inhibited in SFRP2 overexpression of OSCC cell lines (TCA8113), and tumor growth is also reduced in mice subcutaneously inoculated with TCA8113/SFRP2 cells." (PMID 28708091, 2017). "On the other hand, SFRP2 and 4 expression levels often increase during tumourigenesis, likely as a result of increased production by the tumour stroma." (PMID 28218291, 2017). "Greater video intensity likely occurred secondary to higher antibody conjugation to the microbubbles, which therefore facilitated more frequent antibody-SFRP2 interactions within the tumor vasculature." (PMID 28333964, 2017). "Our TIC analysis also allowed us to examine the relationship between time, and the amount of tumor-bound signal directly attributable to the SFRP2 antibodies." (PMID 28333964, 2017). "Specifically, studies in several malignances have demonstrated downregulation of sFRP2 via epigenetic promoter hypermethylation, suggesting a possible role as a tumor suppressor." (PMID 27821163, 2016). "In the retrospective LS series, hypermethylation frequencies for SFRP2 were significantly higher in all tumor types when compared to normal mucosa." (PMID 26203307, 2015). "The present study demonstrated that SFRP2 mRNA was detected in 97.96% of tumor-adjacent normal tissues, while its expression was only detected in 16.33% of the tumor samples." (PMID 25189527, 2014). "Although SFRP2 is a secreted protein, it has been demonstrated to incorporate into the extracellular matrix and localizes to tumor endothelium." (PMID 24489757, 2014). "An increase in SFRP2 as tumor volumes increase would support the theory that SFRP2 stimulates tumor growth; and a decrease in SFRP2 while tumors grow would support the theory that SFRP2 is a tumor suppressor." (PMID 24489757, 2014).
tumor (continued). "Similar to these observations, the results of the present study demonstrated that methylation of the SFRP2 promoter in OSCC tissues occurred more frequently than in the normal tumor-adjacent tissues (75.51 vs. 6.12%)." (PMID 25189527, 2014). "Our data show that SFRP2 expression increased as tumor volume increased in vivo, providing further support for the role of SFRP2 as a stimulator of tumor growth." (PMID 24489757, 2014). "SFRP2 is a 33 kDa secreted protein involved in the Wnt signaling pathway, an important pathway in tumor biology." (PMID 24489757, 2014). "sFRP2 mAb has been shown to induce anti-tumor and anti-angiogenic effects in vitro and inhibit activation of β-catenin and nuclear factor of activated T-cells c3 (NFATc3) in endothelial and tumor cells." (PMID 26056595, 2014). "Recent epigenetic studies have demonstrated that silencing of the SFRP2 by promoter methylation at CpG islands enhanced tumor growth and expansion in GC." (PMID 25202403, 2014). "The use of MSCs as a targeted delivery vector for the exogenously expressed Wnt antagonist, secreted frizzled related protein-2 (SFRP2), reduced tumor growth, increased apoptosis and potentiated tumor necrosis." (PMID 20886110, 2010). "SFRP2 is also a tumor suppressor in many cancer types, including colorectal, cervical, breast, and ovarian, and is inactivated by hypermethylation of its promoter." (PMID 20069066, 2010). "We were able to employ MSCs to target regrowing prostate tissue and deliver SFRP2, antagonizing Wnt-mediated tumor progression." (PMID 20886110, 2010). "The overexpression of SFRP2 by MSCs homed to the tumors and restored tumor responsiveness to castration." (PMID 20886110, 2010). "Within the top 20 genes ranked by Notch pathway-guided COCA, there are several genes related to differentiation (Tdgf1, Egr1 and Lefty1), cell growth (Ddit4, Hk2, Phlda2, Egln3 and Igfbp1) and tumor/cancer development (Afp, Sfrp2, Egr1, Hk2 and Phlda2)." (PMID 20353603, 2010). "Altogether, our data support the proposed tumor suppressive function of SFRP2 in normal breast tissue." (PMID 18990230, 2008). "Therefore, SFRP2 is considered an antagonist of the Wnt signaling pathway and a novel tumor suppressor." (PMID 39729237, 2025). "Additionally, SFRP2 methylation has been shown to accelerate cancer cell invasion and tumor progression." (PMID 39729237, 2025). "However, as the tumor microenvironment changes, extensive SFRP2 methylation occurs, leading to reduced tumor inhibition and promoting tumor development through various signaling pathways." (PMID 39729237, 2025). "Moreover, cases with positive SFRP2 hypermethylation in blood, stool samples, and tumor tissue exhibited lower overall survival compared to negative SFRP2 methylation cases." (PMID 40109625, 2025). "However, SFRP2, SPINK1, CXCL11, CXCL13, and CXCL10 exhibited gene copy loss in certain tumor populations." (PMID 38577604, 2024). "In addition, we also found that SFRP2 expression was lower in the tumor area in comparison with the NAT area (p < 0.001)." (PMID 38802858, 2024). "Those further indicate the relevance and potential role of SFRP2 in AEGJ tumor metastasis." (PMID 39850884, 2024).